HAPLN2 (hyaluronan and proteoglycan link protein 2)
Description:
Mediates a firm binding of versican V2 to hyaluronic acid. May play a pivotal role in the formation of the hyaluronan-associated matrix in the central nervous system (CNS) which facilitates neuronal conduction and general structural stabilization. Binds to hyaluronic acid (By similarity).
Synonyms: BRAL1
Tractability: Antibody: UniProt places it where antibodies can reach, with medium confidence; UniProt predicts a signal peptide or a membrane-spanning region; its Gene Ontology location is reachable by antibodies, with medium confidence.
Gene: Protein-coding gene on chromosome 1 (156,619,331 to 156,626,361, forward strand). Ensembl gene ENSG00000132702.
Subcellular location: Secreted, extracellular space, extracellular matrix
Gene Ontology:
Molecular function: protein binding; hyaluronic acid binding
Biological process: central nervous system development; skeletal system development; cell adhesion
Cellular component: gel phase of interstitial matrix; extracellular matrix; perineuronal net; synapse; node of Ranvier
Genetic constraint (gnomAD): Loss-of-function variants: 28 observed, 27.36 expected, observed/expected ratio (o/e) 1.02, 90% interval 0.76 to 1.4. The upper end of that interval is the gene's LOEUF score, 1.4, which puts it in group 5 of 6, group 1 being the genes least tolerant of losing a copy. Missense variants: 454 observed, 426.44 expected, observed/expected ratio (o/e) 1.06, 90% interval 0.99 to 1.15. Synonymous variants: 208 observed, 178.29 expected, observed/expected ratio (o/e) 1.17, 90% interval 1.04 to 1.31.
Homologues: Orthologues: chimpanzee HAPLN2 (99% identical), macaque HAPLN2 (98% identical), pig HAPLN2 (94% identical), dog HAPLN2 (93% identical), mouse Hapln2 (92% identical), guinea pig HAPLN2 (91% identical), rat Hapln2 (88% identical), tropical clawed frog hapln2 (62% identical), zebrafish hapln2 (53% identical). Paralogues in human: HAPLN3 (47% identical), HAPLN4 (45% identical), HAPLN1 (44% identical), NCAN (37% identical), BCAN (36% identical), VCAN (34% identical), ACAN (34% identical).
Diseases named in the same sentence as HAPLN2 in open-access papers:
HAPLN2 is named in the same sentence as 12 diseases in open-access papers, as found by Europe PMC text mining. Sharing a sentence is not in itself a finding about the gene and the disease. The quoted sentences say what the papers report.
schizophrenia (5 papers, 2016 to 2023). A major psychotic disorder characterized by abnormalities in the perception or expression of reality. "Several studies have revealed the involvement of Hapln2 in the pathogenesis of neurological diseases including PD, AD and schizophrenia, which provided new insights into the underlying molecular mechanisms of brain disorders." (PMID 30949044, 2019). "More studies should focus on the molecular mechanism of Hapln2 in the pathogenesis of schizophrenia using animal models and clinical analysis." (PMID 30949044, 2019). "Hapln2 represents another potential contributor, as a shotgun proteomic analysis of postmortem anterior temporal lobe tissues showed that Hapln2 protein levels are lower in schizophrenia patients than in control subjects." (PMID 30949044, 2019). "The Hapln2 expression levels were remarkably reduced in schizophrenia anterior temporal lobe, while Hapln2 has been recently shown to be accumulated in the neurofibrillary tangle of Alzheimer's brain." (PMID 27601993, 2016). "Additionally, the expression levels of Hapln2 showed lower in the anterior temporal lobes of individuals with schizophrenia than those of healthy subjects." (PMID 30949044, 2019). "As one of the important components of ECM, Hapln2 may be involved in the pathogenesis of schizophrenia through regulating the neuronal migration and velocity of nerve conduction." (PMID 30949044, 2019). "The colocalization of Hapln2 with E3 ligases revealed in our previous work suggests a potential function of Hapln2 in the UPP, which suggesting that Hapln2 may also contribute to the pathophysiology of schizophrenia through dysfunction of UPP." (PMID 30949044, 2019).
Parkinson disease (4 papers, 2016 to 2025). A progressive degenerative disorder of the central nervous system characterized by loss of dopamine producing neurons in the substantia nigra and the presence of Lewy bodies in the substantia nigra and locus coeruleus. "Studies have revealed that Hapln2 promotes the aggregation of α-synuclein, thereby contributing to neurodegeneration in Parkinson’s disease (PD), and it was recently suggested to be in intracellular neurofibrillary tangles (NFTs)." (PMID 30949044, 2019). "Immunoblotting showed that expression levels of Hapln2 were markedly upregulated in the substantia nigra of either human subjects with Parkinson's disease compared with healthy control." (PMID 27601993, 2016). "Hapln2 supports formation of the blood–nerve barrier but elevated levels may also contribute to neurodegeneration during AD or Parkinson's disease." (PMID 40979532, 2025).
dementia (1 paper, 2025). Loss of intellectual abilities interfering with an individual's social and occupational functions. "We stained HAPLN2 in the cerebellum of human brains in their sixties or eighties without dementia." (PMID 40811716, 2025).
epilepsy (1 paper, 2023). A brain disorder characterized by episodes of abnormally increased neuronal discharge resulting in transient episodes of sensory or motor neurological dysfunction, or psychic dysfunction. "Thus, Hapln2 regulates the development of epilepsy by affecting the expression of ECM-related proteins." (PMID 37065920, 2023). "Nevertheless, the Ctla2a and Hapln2 genes have not been adequately studied in epilepsy, and further research is required to determine their possible significance to epilepsy." (PMID 37065920, 2023).
glioma (1 paper, 2025). A benign or malignant brain and spinal cord tumor that arises from glial cells (astrocytes, oligodendrocytes, ependymal cells). "All three DEGs encoding proteoglycans (HAPLN2, ACAN and HAPLN1) showed higher transcript enrichment in the grade 2 gliomas in comparison to the matched normal samples." (PMID 41366031, 2025).
malignant glioma (1 paper, 2018). A grade III or grade IV glioma arising from the central nervous system. "Sim and colleagues found that HAPLN2, also known as BRAL1, was virtually absent in malignant gliomas." (PMID 30356407, 2018).
memory impairment (1 paper, 2026). "Hapln2 overexpression in oligodendrocytes of young mice recapitulated age-related memory impairments." (PMID 41676692, 2026).
neurological disease (3 papers, 2016 to 2023). "This review article summarizes recent progress focusing on the roles of Hapln2 in the central nervous system (CNS) under physiological and pathological conditions, highlighting the therapeutic potential of Hapln2 in neurological diseases." (PMID 30949044, 2019). "Together, these studies implicate the involvement of Hapln2 in the pathological processes of neurological diseases." (PMID 30949044, 2019). "However, further studies of animal and clinical experiments are needed to clarify these mechanisms and the precise role that Hapln2 plays in these neurological disorders in the future." (PMID 30949044, 2019). "In conclusion, as a novel brain specific-hyaluronan and protoglycan link protein, the knowledge of the function of Hapln2 in neurological diseases is still lacking." (PMID 27601993, 2016).
neurodegenerative disease (1 paper, 2024). A disorder of the central nervous system characterized by gradual and progressive loss of neural tissue and neurologic function. "The protein HAPLN2 (Hyaluronan and proteoglycan link protein 2) is important in the organization of the extracellular matrix in the brain and is implicated in neurodegenerative disease." (PMID 39234409, 2024). "Taken together, disruption of the extracellular matrix and HAPLN2 likely plays an important dynamic role in neural protection against MS and other neurodegenerative diseases." (PMID 39234409, 2024).
tumor (1 paper, 2021). "Silencing of genes involved in cell adhesion may lead to tumor aggressiveness and tumor progression, as was shown for CD97, CTNNA1, DLC1, and HAPLN2 genes in which hypermethylation was associated with poorer survival of patients with ovarian cancer." (PMID 33921911, 2021).
HAPLN2 also shares sentences with these, for which no sentence is quoted: Alzheimer disease (2 papers); brain disorder (1).